OSTC (oligosaccharyltransferase complex non-catalytic subunit)
Description:
Subunit of STT3A-containing oligosaccharyl transferase (OST-A) complex that catalyzes the initial transfer of a defined glycan (Glc(3)Man(9)GlcNAc(2) in eukaryotes) from the lipid carrier dolichol-pyrophosphate to an asparagine residue within an Asn-X-Ser/Thr consensus motif in nascent polypeptide chains, the first step in protein N-glycosylation. N-glycosylation occurs cotranslationally and the complex associates with the Sec61 complex at the channel-forming translocon complex that mediates protein translocation across the endoplasmic reticulum (ER). Within the OST-A complex, acts as an adapter that anchors the OST-A complex to the Sec61 complex. May be involved in N-glycosylation of APP (amyloid-beta precursor protein). Can modulate gamma-secretase cleavage of APP by enhancing endoprotelysis of PSEN1.
Synonyms: DC2
Tractability: Small molecule: a structure with a bound ligand is known. Antibody: UniProt predicts a signal peptide or a membrane-spanning region. PROTAC: ubiquitination databases record sites on it; its protein half-life has been measured.
Gene: Protein-coding gene on chromosome 4 (108,650,585 to 108,667,820, forward strand). Ensembl gene ENSG00000198856.
Subcellular location: Endoplasmic reticulum; Membrane
Pathways (Reactome):
Disease: Maturation of DENV proteins; Maturation of spike protein
Cell-Cell communication: Regulation of CDH1 posttranslational processing and trafficking to plasma membrane
Immune System: PD-L1(CD274) glycosylation and translocation to plasma membrane
Metabolism of proteins: Asparagine N-linked glycosylation
Gene Ontology:
Molecular function: protein binding; protein-macromolecule adaptor activity; dolichyl-diphosphooligosaccharide-protein glycotransferase activity
Biological process: protein N-linked glycosylation; glycoprotein biosynthetic process
Cellular component: endoplasmic reticulum; endoplasmic reticulum membrane; oligosaccharyltransferase complex; oligosaccharyltransferase complex A; membrane
Genetic constraint (gnomAD): Loss-of-function variants: 10 observed, 11.23 expected, observed/expected ratio (o/e) 0.89, 90% interval 0.55 to 1.5. The upper end of that interval is the gene's LOEUF score, 1.5, which puts it in group 6 of 6, group 1 being the genes least tolerant of losing a copy. Missense variants: 108 observed, 144.98 expected, observed/expected ratio (o/e) 0.74, 90% interval 0.64 to 0.87. Synonymous variants: 53 observed, 57.38 expected, observed/expected ratio (o/e) 0.92, 90% interval 0.74 to 1.16.
Homologues: Orthologues: dog OSTC (99% identical), guinea pig OSTC (99% identical), mouse Ostc (99% identical), pig OSTC (99% identical), rabbit OSTC (99% identical), rat Ostc (97% identical), tropical clawed frog ostc (97% identical), chimpanzee OSTC (97% identical), macaque OSTC (97% identical), zebrafish ostc (93% identical), rat Ostcl1 (87% identical), Drosophila melanogaster CG9662 (62% identical).
Diseases named in the same sentence as OSTC in open-access papers:
OSTC is named in the same sentence as 3 diseases in open-access papers, as found by Europe PMC text mining. Sharing a sentence is not in itself a finding about the gene and the disease.
OSTC shares sentences with these, for which no sentence is quoted: bladder cancer (1 paper); cervical cancer (1); tumor (1).